PTK6 (protein tyrosine kinase 6)
Diseases named in the same sentence as PTK6 in open-access papers (continued):
Sharing a sentence is not in itself a finding about the gene and the disease.
tumor (continued). "Using IHC, strong positivity (2+, 3+) for the HER1 receptor was found in only 5% of the tumours, for HER2 in 26%, for HER3 in 74%, for HER4 in 51%, and for PTK6 in 59%." (PMID 17299391, 2007). "Pharmacological inhibition of PTK6 using XMU-MP-2 effectively reduces the stemness property of CRC cells and improves its chemosensitivity to 5-FU/L-OHP in both nude mice subcutaneously implanted tumor model and PDX model constructed with NOD-SCID mice." (PMID 34551797, 2021). "We selected 30 tumor progression-enriched gene signatures downstream of PSPC1 and PTK6 signaling pathways to demonstrate the significant up-regulation (in red) and down-regulation (in green) of gene expression under PSPC1/PTK6 dynamic interaction and PSPC1-CT131 treatment." (PMID 31844057, 2019). "The significant IC50 shift between the PTK6 kinase inhibition and tumor cell growth inhibition in engineered tumor cells overexpressing PTK6 further confirmed the conclusion that PTK6 kinase inhibition does not lead to tumor cell growth suppression." (PMID 29879184, 2018). "Due to the quantification limitation of low endogenous p-PTK6 levels in tumor cells, we were not able to directly measure the PTK6 kinase activity in correlation to the tumor cell growth." (PMID 29879184, 2018). "In conclusion, novel, potent and selective PTK6 inhibitors and a negative control analogue have been identified to enable a thorough interrogation of the specific role of PTK6 kinase activity in tumor cells." (PMID 29879184, 2018). "Cell growth inhibition by PTK6 inhibitors in PTK6-positive tumor cells and PTK6-negative HEK293T cells." (PMID 29879184, 2018). "So overall the level of PTK6 activation was low and did not mirror the total PTK6 expression in tumor cells." (PMID 29879184, 2018). "Finally, PTK6 downregulation inhibited growth of tamoxifen-sensitive (parental) and tamoxifen-resistant ER+ MCF-7L primary tumor xenografts." (PMID 29167821, 2017). "We previously showed that PTK6 expression is induced in MMTV-ERBB2 transgenic mouse mammary gland tumors, and here we demonstrate that PTK6 expression can be detected in the mammary glands of these mice before tumor development." (PMID 26247733, 2015). "The expression of PTK6 was not significantly correlated with clinical and histopathological parameters, such as lymph node status, tumour size, and histological grade or type." (PMID 18781181, 2008). "Notably, genes such as SHC1 and PTK6 regulate essential signal transduction pathways, including the MAPK and PI3K cascades, which are critical for both tumour cell proliferation and resistance to programmed cell death—mechanisms that have been strongly implicated in therapeutic resistance in ccRCC." (PMID 40830065, 2025). "PTK6 may collaborate with a range of growth factor receptors, including as the ERBB family, IGF1R, and MET, as well as a variety of signaling pathways, such as hypoxia, p27/CDK/Cyclins, ERK1/2/P38 to promote tumor progression." (PMID 38573548, 2024). "Moreover, PTK6 exhibited a significant correlation with TMB and MSI across various tumor types." (PMID 38573548, 2024). "In contrast, PTK6 could not suppress PSPC1-Y523F-induced tumor formation and metastasis and even enhanced these effects." (PMID 31844057, 2019). "The broad kinase selectivity of these PTK6 inhibitors is not known, therefore it is not certain whether the observed inhibitory effects on tumor cells is due to the specific inhibition of PTK6 kinase and/or an off-target effect by affecting other kinases." (PMID 29879184, 2018). "However, the tumor cell growth inhibition shows neither correlation with the PTK6 kinase activity inhibition, nor the total or activated PTK6 protein levels in tumor cells, suggesting that the tumor cell growth is independent of PTK6 kinase activity." (PMID 29879184, 2018). "This array did not include adjacent tumor tissue with high PTK6 expression that could overwhelm or compete with a signal in the normal breast tissue." (PMID 25153721, 2014).
tumor (continued). "When analyzing PTK6 expression in normal and tumor tissue from the same patient, we found that active P-Y342 PTK6 is only detectable in the tumor tissue but not in normal glands, although total PTK6 levels may not change much from normal to tumor tissue." (PMID 25153721, 2014). "The long-term prognostic value of PTK6, namely that it is the strongest prognostic marker at 240 months but not at 60 months may further support a role for PTK6 in promoting differentiation of tumour cells." (PMID 17299391, 2007). "The results demonstrated a positive correlation between PTK6 and Tregs, as well as a negative correlation with CD8+ and CD4+ T cells across most tumor types." (PMID 38573548, 2024). "With PSPC1-CT131 expressed in the nucleus, we suggested that PSPC1-CT131 could bind to the SH3 domain of PTK6 in the nucleus but not PSF in the cytosol, which may serve as an additional mechanism to suppress tumor progression." (PMID 31844057, 2019).
adenocarcinoma (3 papers, 2015 to 2019). A common cancer characterized by the presence of malignant glandular cells. "Ptk6 expression is reduced in human adenocarcinoma, and reduction in Ptk6 also promotes the growth of xenografts." (PMID 30599048, 2019). "Out of the 11 PB-Cre4, Ptenflox/flox, Ptk6−/− mice examined, only one developed adenocarcinoma of the prostate gland (P < 0.05)." (PMID 29142193, 2017).
infection (2 papers, 2013 to 2024). The state of being infected such as from the introduction of a foreign agent such as serum, vaccine, antigenic substance or organism. "Infection of Ptk6 IEC with various B. cereus strains at an MOI of 1 caused rapid cell death with a complete detachment of cells from the tissue culture plate within 4 h." (PMID 23613846, 2013). "Administration of succinate, which mimics infection and activates tuft cells, revealed PTK6-dependent activation of innate immune responses in male but not female mice." (PMID 39461944, 2024). "Analysis of RNA-seq data from mice infected with Heligmosomoides bakeri (Hb), showed increased expression of Ptk6 at 24 h after infection." (PMID 39461944, 2024). "We detected upregulation of Ptk6 upon infection with helminths and bacteria." (PMID 39461944, 2024).
Lung (2 papers, 2017 to 2024). "The GEO cohort (GSE30219) of Lung patients were analyzed using the TIDE database, comparing with the PTK6 low expression group, the PTK6 high expression group had a poor OS." (PMID 38573548, 2024).
gynecological tumors (1 paper, 2024). "Abnormal expression of protein tyrosine kinase 6 (PTK6) has been proven to be involved in the development of gynecological tumors." (PMID 38573548, 2024).
PTK6 also shares sentences with these, for which no sentence is quoted: non-small cell lung carcinoma (4 papers); skin cancer (2); thyroid cancer (2); acute myeloid leukemia (1); Alzheimer disease (1); Autoimmunity (1); B-cell lymphoma (1); cholangiocarcinoma (1); colorectal tumors (1); COVID-19 (1); glioblastoma (1); head and neck squamous cell carcinoma (1); Immunodeficiency (1); intestinal tumors (1); kidney clear cell carcinoma (1); lung squamous cell carcinoma (1); lupus (1); mesothelioma (1); metastasis (1); metastatic carcinoma (1); metastatic melanoma (1); neurologic diseases (1); oral cancers (1); osteosarcoma (1); pancreatic ductal adenocarcinoma (1); pheochromocytoma and paraganglioma (1); renal carcinoma (1); serous ovarian carcinoma (1); small cell lung carcinoma (1); uterine corpus endometrial carcinoma (1).